TLR4 (toll like receptor 4)
Diseases named in the same sentence as TLR4 in open-access papers (continued):
Sharing a sentence is not in itself a finding about the gene and the disease.
myeloma (26 papers, 2010 to 2025). "In support, a recent study by our group has shown that certain polymorphisms in TLR4 pathway are associated with poor outcome in myeloma patients." (PMID 30824741, 2019). "Our results provide evidence that LPS-mediated TLR4 stimulation promotes myeloma cell growth and survival by suppressing apoptosis associated with integrated stress response and UPR activation through PERK-CHOP signaling." (PMID 30824741, 2019). "Moreover, TLR4 was shown to be associated with the myeloma tumor microenvironment and bortezomib resistance." (PMID 36401285, 2022). "Multiple myeloma cells were studied in research that demonstrated the important role of TLR4 signaling as a regulator for other cells in the proinflammatory microenvironment." (PMID 38379331, 2024). "Toll-like receptor 4 (TLR4) signaling plays an important role in multiple myeloma (MM) by maintaining cancer mitochondrial metabolism." (PMID 37055798, 2023). "This study defines ectopic mitochondrial chaperonin 60 (CH60) on the multiple myeloma cell surface as a HAPLN1 matrikine receptor that signals via TLR4 to induce NF-κB signaling and drug resistance." (PMID 36625202, 2023). "Recently, we demonstrated that TLR4 regulates mitochondrial biogenesis in myeloma PCs, and this pathway is upregulated in proteasome inhibitor-resistant cells." (PMID 35453452, 2022). "The expression of TLR4 mRNA was also determined in CD138+ myeloma cells isolated from the bone marrow of 16 patients at time of diagnosis." (PMID 30824741, 2019). "We found that TLR4 activation by LPS significantly decreased CHOP transcript levels in all four multiple myeloma cell lines studied." (PMID 30824741, 2019). "The expression pattern of TLR4 has been previously investigated in myeloma, and it was found to be highly expressed in most myeloma cell lines, as well as in primary myeloma cells." (PMID 30824741, 2019). "Our study confirms that TLR4 is expressed in myeloma cells as shown by the expression pattern of most myeloma cell lines examined and of 16 CD138+ selected myeloma patient bone marrow samples." (PMID 30824741, 2019). "PD-L1 expression is promoted by Toll-like receptor 4- (TLR4) stimulation in human multiple myeloma-derived plasma cells, and this PD-L1 expression is dependent on the mitogen- activated protein kinase (MAPK) signal pathway." (PMID 29728568, 2018). "Interestingly, a proportion of both CH60 and TLR4 puncta was seen unassociated with each other on the plasma membrane, suggesting that they can exist independently at the myeloma cell surface." (PMID 36625202, 2023). "In this regard, selective blockade of TLR-4 reduced myeloma progression in murine myeloma models." (PMID 37744361, 2023). "Since stimulation of TLR4 induces Nrf2 nuclear translocation as well as its downstream antioxidant enzyme HO-1 in myeloma PCs, the current study supports the notion that TLR4 and HO-1 signaling pathways, both upregulated after BTZ treatment, activated each other." (PMID 35453452, 2022). "In particular, activation of TLR4 by lipopolysaccharide (LPS) influences mitochondrial dynamics in myeloma PCs and contributes to bioenergetic changes in PCs resistant to proteasome inhibitors including an increase in mitochondrial mass and an increased reliance on mitochondrial respiration." (PMID 35453452, 2022). "In a final series of experiments, we wanted to clarify whether HO-1 could regulate TLR4 expression in myeloma PCs." (PMID 35453452, 2022). "To investigate whether TLR4 may be involved in the mitochondria biogenesis of human myeloma cell lines (HMCLs), we evaluated the effect of the activation of this pathway on mitochondrial mass." (PMID 32707760, 2020). "We showed that exposure of MM cell lines to LPS, prior to treatment with BTZ, could partially protect cells from BTZ-induced apoptosis; this effect was also evident after TLR4 knockdown in myeloma cells." (PMID 30824741, 2019).
myeloma (continued). "We show here that TLR4 and TLR9 signaling downregulated BCMA in MM cells at both the gene and protein levels and that approximately 50% of patients’ myeloma cells also respond to TLR activation by downregulating BCMA." (PMID 38911853, 2024). "The inhibition of DUSP represses H2O2-induced senescence in myeloma cells, whereas overexpression of DUSP or inhibition of TLR4 facilitates senescence." (PMID 38001481, 2023). "Moreover, we recently demonstrated that TLR4 signalling plays a key role in mesenchymal stromal cells (MSC) transformation by inducing a proinflammatory phenotype associated with a protumor behaviour, allowing immune escape mechanisms and tumor growth in the myeloma microenvironment." (PMID 32707760, 2020). "As TLR4 activation in myeloma cells suppresses ER stress, reducing the efficacy of BTZ, we evaluated herein the role of TLR4 signalling on MM cells’ mitochondrial dynamics and energy metabolism as the potentially active mechanism of drug resistance to BTZ." (PMID 32707760, 2020). "Analysis of toll-like receptor (TLR) expression at protein level indicated that TLR1, TLR3, TLR4, TLR7, TLR8, and TLR9, were similarly expressed in most human myeloma cell lines, including L363 and RPMI 8226 cells, as well as in primary cells from MM patients." (PMID 28702457, 2017). "Andrographolide suppresses toll-like receptor 4 (TLR4) expression and NF-κB signaling in multiple myeloma cells at 10 μM14." (PMID 28680097, 2017). "Expression of mRNA for TLR1, TLR3, TLR4, TLR5, TLR7, TLR8, and TLR9 was found in all myeloma cell, but levels of mRNA expression differed amongst different cell lines." (PMID 23593278, 2013). "MDSC production of S100A9, a calcium-binding protein that promotes the release of TNF-α, IL-6, and IL-10 in autocrine pathway through TLR4 interaction, attracts myeloma cells in the TME and supports myeloma cell growth via the activation of the canonical NFκB pathway." (PMID 36726975, 2022). "TLR4 staining by immunohistochemistry (IHC) has been examined in a number of hematologic malignancies and increased expression can be demonstrated on tumor cells in diffuse large B-cell lymphoma (DLBCL), multiple myeloma, and B acute lymphoblastic leukemia (B-ALL)." (PMID 32974162, 2020).
chronic periodontitis (25 papers, 2008 to 2025). A chronic inflammatory process that affects the tissues that surround and support the teeth. "Three SNPs of TLR4, i.e., rs1927911 (TT/CC+CT), rs2149356 (TT/GG+GT) and rs2737190 (GG/AA+AG), were associated with moderate/severe chronic periodontitis in Chinese population infected with P. gingivalis." (PMID 31772831, 2019). "The correlation between SNPs of TLR4 and chronic periodontitis susceptibility in the whole subjects and the patients detected with P. gingivalis was investigated." (PMID 31772831, 2019). "However, results on the relationship of TLR4 SNPs and periodontitis were inconsistent, especially in patients with chronic periodontitis (Chrzeszczyk, Konopka & Zietek, 2015; Song, Kim & Lee, 2013)." (PMID 31772831, 2019).
dengue (25 papers, 2008 to 2025). "A study conducted of children in Indonesia showed that the presence of the Asp299Gly and Thr399Ile SNPs in TLR4 favors the susceptibility to infection and the severity of dengue in this population." (PMID 33138336, 2020). "For DENV infection, a variant in the promoter region of the DENV receptor DC-SIGN/CD209 and the pattern recognition receptor (PRR) Toll-like receptor 4 (TLR4) haplotypes have been found associated with severity of dengue disease." (PMID 32576686, 2020). "During DENV infection, an association between TLR4 and severe dengue has already been seen." (PMID 35632732, 2022). "Furthermore, TLR4 antagonist and anti-TLR4 antibody treatment inhibited the vascular leakage, a characteristic hallmark of dengue disease severity." (PMID 27473856, 2016). "NS1 facilitates viral replication, activates Toll-like receptor 4 (TLR-4) in monocytes and macrophages, and triggers pro-inflammatory cytokines, which contribute to the vascular permeability linked with severe dengue." (PMID 39998044, 2025). "In 2010, we reported that CD14 (+) monocytes expressing TLR2 and TLR4 were increased in peripheral blood from mild dengue patients compared to severe ones." (PMID 35632732, 2022). "SARS-CoV-2 and other viruses, including RSV, Ebola, and dengue, also activate toll-like receptor-4 (TLR4) to induce the inflammatory response." (PMID 34566657, 2021). "Because DENV NS1 can activate inflammation through Toll-like receptor 4 (TLR4), NS1 is considered as one of the viral factors on the induction of dengue associated inflammation." (PMID 33995345, 2021). "The analysis showed that TLR4-rs2737190-G/G and TLR4-rs11536865-G/C genotypes and TGCG haplotype were associated with protection from dengue." (PMID 33138336, 2020). "In conclusion, the TLR4-rs2737190-G/G and TLR4-rs11536865-G/C genotypes and TGCG haplotype were associated with protection from dengue." (PMID 33138336, 2020). "Dengue patients with high levels of monocytes and low levels of lymphocytes were more likely to be TLR4-rs2737190-A/A and A/G." (PMID 33138336, 2020). "The codominance model showed that dengue patients had a lower probability of presenting the TLR4-rs2737190-G/G genotype (odds ratio (OR) (95% CI) = 0.34 (0.14–0.8), p = 0.038)." (PMID 33138336, 2020). "We evaluated NO, NS1 serum levels (ELISA), TNF-α production by peripheral blood mononuclear cells (PBMCs), and TLR4 expression on CD14+ cells from 37 dengue patients and 20 healthy controls." (PMID 25580138, 2014). "DENV NS1 TLR4-dependent activity, which is hypothesized to induce endothelial vascular leak during severe dengue, could be inhibited by the use of TLR4 blocking antibodies and antagonists, which was demonstrated in vivo in a mouse model." (PMID 36016430, 2022). "VDR and TLR4 but not TLR2gene polymorphisms were found to be associated with dengue susceptibility in Indian population." (PMID 34602778, 2021). "In a previous study, a differentially expressed TLR profile was reported in children with severe dengue, wherein increased expression of TLR7 and TLR4 transcript variant 3 (TLR4R3) and decreased expression of TLR1, TLR2, TLR4R4, and TLR4 cofactor CD14 were observed." (PMID 34603272, 2021). "In addition, CD14(+) monocytes expressing TLR2 and TLR4 were increased in peripheral blood from mild dengue patients compared to in that of patients with severe dengue, suggesting the protective role of TLR2 and TLR4 in this setting." (PMID 34603272, 2021). "In this study, we demonstrated that DENV NS1 in the concentration, which is within the range of NS1 in dengue patients’ sera (0.01–50 μg/ml), could activate platelets and induce apoptosis in a dose-dependent manner through TLR4 signal transduction." (PMID 31009511, 2019).
dengue (continued). "While it is currently not understood how TLR4 may detect orthohantavirus infection, recent work has demonstrated TLR4 activation by viral glycoproteins belonging to other viral families, including Dengue, Ebola, SARS-CoV-2, respiratory syncytial, and vesicular stomatitis viruses." (PMID 37243216, 2023). "The TLR4-rs11536865 polymorphism (promoter-728, C/G) had not been associated with infectious diseases; however, a systematic analysis of this study shows that dengue patients had a higher probability of presenting allele G than GP individuals." (PMID 33138336, 2020). "Early in infection, increased expression of TLR4 in monocytes of patients with dengue fever (DF) was detected compared to patients with dengue hemorrhagic fever (DHF)." (PMID 25580138, 2014). "Interestingly, association of allelic polymorphisms of TLR4 with DSS suggested by De Kruif and colleagues suggests that differential signalling through TLRs may contribute to the severity of dengue disease, as suspected for other pathologies." (PMID 20652028, 2010). "We reported that monocytes from dengue patients, as well as DENV-2-infected monocytes in vitro, exhibit increased expression of TLR2 and TLR4, which supports the involvement of TLR activation during infection." (PMID 41012652, 2025). "The relationships between in vivo dengue virus nonstructural protein 1 (NS1) levels and innate immune response parameters (TLR4 expression and TNF-α/NO production) in infected dengue patients were investigated in our work." (PMID 25580138, 2014). "Besides the importance of NS1 in the dengue viral life cycle, NS1 can disrupt the complement system, induce endothelial hyperpermeability and activate cells via toll-like receptor 4, suggesting multiple roles of NS1 during the course of dengue infection." (PMID 40284984, 2025). "For example, DENV-infected patients suffering from a more severe form of dengue with hemorrhagic fever in comparison to the patients with milder dengue, displayed higher NS1 serum levels correlated with low TLR4 expression and impaired TLR4 signaling during the acute febrile phase of the disease." (PMID 36016430, 2022). "A vascular leak in endothelial cells, characteristic of the severe dengue form, is hypothesized to be triggered by DENV NS1, and by TLR4-dependent, and independent mechanisms." (PMID 36016430, 2022). "Dengue patients with high levels of monocytes and low levels of lymphocytes, and DHF patients with high levels of IgM and IgG and low levels of leukocytes, had a higher probability of being TLR4-rs4986791-C/C." (PMID 33138336, 2020). "In addition, dengue patients with high levels of monocytes and low levels of lymphocytes, and DHF patients with high levels of IgM and IgG, were more likely to be TLR4-11536865-G/G." (PMID 33138336, 2020). "Thus, the aim of this study was to investigate the relationships between in vivo secreted levels of NS1 and innate immune response parameters (TLR4 expression and TNF-α/NO production) in infected dengue patients with different clinical outcomes." (PMID 25580138, 2014). "Therefore, we evaluated the expression levels of TLR2, TLR3, TLR4 and TLR9 in mDCs, pDCs and monocytes of dengue patients, and compared them to the HCs." (PMID 23469297, 2013). "In mDCs of dengue patients, TLR3, TLR4 and TLR9 reached maximum expression on day 5 of illness." (PMID 23469297, 2013). "Furthermore, the NS1 did not potentiate the TLR4 response to LPS making this unlikely to be a contributory function for NS1 in dengue pathology." (PMID 41218088, 2025). "Here we show that dengue NS1 produced in mammalian cells does not activate TLR4." (PMID 41218088, 2025). "Notably, the lack of TLR4 stimulation by NS1 protein does not exclude a role for TLR4 in dengue disease as it may be activated by LPS influx from the gut or by putative endogenous stimulatory lipids." (PMID 41218088, 2025).
dengue (continued). "TLR functions as receptors during dengue infection are not yet clear and our data indicates a differential regulation of TLR4 expression and responsiveness during the acute phase of this illness on cells from DHF when compared to DF patients and that may be also affected by NS1 serum levels." (PMID 25580138, 2014). "Since we showed that recombinant NS1 does not activate TLR4, a key question was whether NS1 released from DENV-infected cells, which is likely to resemble the NS1 produced during dengue disease, can activate TLR4." (PMID 41218088, 2025). "Notably, human TLR4 interacts with DENV non-structural protein 1 (NS1) on endothelial cells and contributes to vascular leakage in dengue shock." (PMID 36070318, 2022).
emphysema (25 papers, 2007 to 2024). "They described developing emphysemas in naive TLR4- and MyD88-deficient mice beginning at 3 months after birth and peaking between 6 months and 1 year." (PMID 38397817, 2024). "Reduced TLR4 expression in the lungs was associated with airflow limitation and emphysema in smokers." (PMID 35055174, 2022). "A clinical study found that the extent of down-regulated TLR4 expression in the lungs was associated with the severity of emphysema and airflow limitation in smokers." (PMID 31847115, 2019). "In human emphysema, reduced TLR4 expression has been associated with more severe emphysema and airflow obstruction." (PMID 30790400, 2019). "We demonstrate that lungs and Ec deficient in TLR4 gene exhibit a senescence phenotype in vivo and that lung‐targeted silencing of Ec‐p16INK4a prevents age‐related emphysema in TLR4−/− mice." (PMID 30790400, 2019). "We previously reported that a physiologic consequence of TLR4 deficiency is postdevelopmental, age‐related spontaneous emphysema, and identified increased oxidant production via NADPH oxidase 3, as a potential mechanism in lung Ec." (PMID 30790400, 2019). "Experimentally, emphysema progression in TLR4-deficient mice can be halted by a Nox inhibitor or Nox3 siRNA." (PMID 26617525, 2015). "To further explore the requirement for Mal in lung pathology, we assessed its role in two cellular mechanisms, apoptosis and oxidative stress, which are associated with emphysema in Tlr4−/− (and MyD88−/−) mice." (PMID 24205107, 2013). "Previously, intracellular oxidants such as those derived from the NADPH oxidase (Nox) system have been implicated in disease states, and TLR4 deficiency in mice led to the up-regulation of Nox3 in lungs which correlated with the emphysema phenotype." (PMID 24205107, 2013). "Another major cellular process associated with the development of human emphysema and animal models of emphysema, including TLR4-deficient mice, is apoptosis." (PMID 24205107, 2013). "Recent evidence has demonstrated that mice deficient in the TLR4 gene developed pulmonary emphysema." (PMID 22251849, 2012). "This study demonstrated that the rs11536889 (+3725 G/C) SNP and the haplotype that carried the minor C allele of this SNP in the TLR4 gene were likely associated with the risk of developing the emphysema phenotype in the Japanese population." (PMID 22251849, 2012). "Down-regulated TLR4 expression in lung was associated with emphysema and airflow limitation in smokers." (PMID 23170858, 2012). "Several studies have shown that defects in innate TLR4-mediated immunity can be associated with emphysema." (PMID 23170858, 2012). "TLR4 expression seemed associated with emphysema severity which was reported to be more correlated with airflow limitation (FEV1/FVC) than COPD stage defined by FEV1 (% predicted)." (PMID 23170858, 2012). "The minor C allele of the rs11536889 SNP in the TLR4 gene is likely associated with the risk of developing emphysema in the Japanese population." (PMID 22251849, 2012). "In conclusion, down-regulated TLR4 expression in lung was associated with emphysema and airflow limitation in smokers." (PMID 23170858, 2012). "The present study showed the minor C allele and the CC genotype of the rs11536889 SNP in the TLR4 gene were likely associated with the emphysema phenotype of COPD in Japanese subjects." (PMID 22251849, 2012). "This is in accordance with previous studies where an aberrant innate immune response, being demonstrated by alterations of lung cytokines, oxidant stress, and TLR4 signaling, has been associated with experimental emphysema." (PMID 20169003, 2009). "Mice exposed chronically to cigarette smoke develop emphysema and increased expression of Toll-like receptor (TLR4), but Tlr4 deficiency further enhances the development of emphysema and is associated with increased expression of autophagy markers, such as LC3." (PMID 35608088, 2022).